RNU7-151P (RNA, U7 small nuclear 151 pseudogene)
Gene: Small nuclear RNA gene on chromosome 4 (102,837,047 to 102,837,099, reverse strand). Ensembl gene ENSG00000252739.
Homologues: Orthologues: chimpanzee U7 (94% identical), tropical clawed frog U7 (70% identical), tropical clawed frog U7 (68% identical), tropical clawed frog U7 (66% identical), tropical clawed frog U7 (64% identical), tropical clawed frog U7 (62% identical), tropical clawed frog U7 (60% identical), tropical clawed frog U7 (58% identical), tropical clawed frog U7 (55% identical). Paralogues in human: RNU7-62P (83% identical), RNU7-113P (79% identical), RNU7-141P (79% identical), RNU7-24P (79% identical), RNU7-28P (79% identical), RNU7-60P (79% identical), RNU7-67P (79% identical), RNU7-80P (79% identical), RNU7-13P (77% identical), RNU7-167P (77% identical), RNU7-35P (77% identical), RNU7-3P (77% identical), and 142 more.